RBP4 (retinol binding protein 4)
Diseases named in the same sentence as RBP4 in open-access papers (continued):
Sharing a sentence is not in itself a finding about the gene and the disease.
diabetes (continued). "Fasting plasma levels of glycated hemoglobin, leptin, pro-insulin and retinol binding protein 4 differed between impaired fasting glucose/impaired glucose tolerance and normal subjects group and between newly detected diabetes and normal subjects group." (PMID 29610560, 2018). "In those patients with diabetes, plasma levels of RBP4 were positively correlated with HbA1c (r = 0.347, P<0.0001), BMI (r = 0.163, P=0.001), Hs-CRP (r = 0.302, P<0.001), and duration of illness (r = 0.179, P<0.001)." (PMID 30135138, 2018). "This phenomenon was in accordance with the previous results that RBP4 increased in diabetes patients with coronary heart disease and cerebral infarction and was negatively associated with carotid intima-media thickness." (PMID 30186876, 2018). "Many authors found that RBP-4 levels were associated with MetS parameters and HOMA-IR, the duration of diabetes and carotid atherosclerosis as determined by CIMT." (PMID 28977161, 2017). "These adipokines including leptin, visfatin, resistin, apelin, vaspin, and retinol binding protein-4 can regulate inflammatory responses and contribute to the pathogenesis of diabetes." (PMID 23772224, 2013). "Our study added to the growing evidences that serum RBP4,which secreted mainly by liver and adipose tissue, was a potential adverse impact factor for beta cell function and diabetes mellitus mellitus." (PMID 24160775, 2013). "Percentage prevalence of diabetes increased with increase in number of risk alleles when analyzed with sentinel SNPs in STRA6 (rs736118), RBP4 (rs3758539) and GLUT4 (rs5435)." (PMID 20625434, 2010). "As a presumably non-specific aptamer library, we chose a polyclonal library, which had previously been evolved and characterized during the development of a sensor-based assay for the quantification of the retinol-binding protein 4 (RBP4) as a potential diabetes-type-2 marker." (PMID 41002345, 2025). "Thus RBP4 plays a key role in the occurrence and development of diabetes and other related diseases." (PMID 37312059, 2023). "We found that in the middle aged and elderly population without diabetes at baseline, baseline higher RBP4 levels were associated with increased BMI, waist circumference, fasting and OGTT 2-h plasma glucose triglyceride, and total cholesterol." (PMID 35634496, 2022). "RBP4 has been regarded as an important serological biomarker for type 2 diabetes mellitus (T2DM)." (PMID 36139080, 2022). "Instead, more studies indicated RBP4 levels were positively associated with visceral body fat or abdominal fat mass in individuals with or without diabetes or in healthy women 21 to 67 years old." (PMID 35634496, 2022). "The aim of our study was to determine the concentrations of adipokines: fetuin A, fatty acid binding protein 4 (FABP4) and retinol binding protein 4 (RBP4) in Cushing’s syndrome and to assess their relation to established cardiovascular and diabetes risk markers." (PMID 36561568, 2022). "Retinol binding protein 4 (RBP4) has been shown to induce IR in type 2 diabetes mellitus." (PMID 34177800, 2021). "Complications of CAD may enhance the increase in RBP4 levels, as increasing RBP4 levels were also observed in patients with diabetes and metabolic syndrome." (PMID 34419052, 2021). "Exploring des‐acyl ghrelin's influence on the expression of RBP4, which has been shown to reduce insulin sensitivity, leading to diabetes, revealed that des‐acyl ghrelin treatment of C2C12 cells leads to a time‐ and dose‐dependent increase in the mRNA levels of RBP4." (PMID 33463908, 2021). "So, the elevation of RBP4 level can be a sign for catching the diabetes." (PMID 31953481, 2020). "In multivariable linear regression analysis adjusted for age, sex, diabetes status and the use of glucose lowering and antihypertensive medication, it was demonstrated that RBP4 was independently related to large VLDL particles, as well as to small LDL particles." (PMID 31717719, 2019).
diabetes (continued). "In men, all variables that we had examined did not modify the risk association between RBP4 and type 2 diabetes, and the RBP4-diabetes association stayed largely null and non-significant in all subgroups." (PMID 30651745, 2019). "Interestingly, the combined model I (RBP4/HOMA-IR/diabetes duration) improved the ability of every single marker to diagnose DR (AUC of the combined model 0.84; 95% CI: 0.78–0.90; P<0.01)." (PMID 30135138, 2018). "Furthermore, RBP4 also had been suggested as a useful marker of overall metabolic control in Chinese patients with type 2 diabetes mellitus." (PMID 30135138, 2018). "In addition, relationships have been found between RBP4 and diabetes complications, such as atherosclerosis and CVD." (PMID 29747616, 2018). "Interestingly, the combined model (RBP4/HOMA-IR/diabetes duration) improved the ability of every single marker to diagnose VTDR (AUC of the combined model 0.93; 95% CI: 0.86–0.96; P<0.01)." (PMID 30135138, 2018). "Furthermore, the combined model II (RBP4/HOMA-IR/diabetes duration/Hs-CRP/HbA1c) improved the ability of every single marker and model I to diagnose DR (AUC of the combined model 0.87; 95% CI: 0.80–0.92; P<0.05)." (PMID 30135138, 2018). "Therefore, the objectives of our research are to investigate the relationship between RBP4 and vitamin D and to explore the role of vitamin D intervention through the construction of streptozotocin-induced diabetic and diabetic atherosclerosis rat models." (PMID 30186876, 2018). "In the current study we found that serum RBP4 levels were inversely associated with β cell function in a cohort of Chinese women NAFLD patients without known diabetes mellitus." (PMID 24160775, 2013). "So, lowering the serum RBP4 levels may be an effective strategy for the prevention and treatment of type 2 diabetes mellitus." (PMID 24250489, 2012). "Taken together, these findings suggest that low plasma RBP4 may serve as a broadly applicable prognostic biomarker in maintenance hemodialysis patients, regardless of sex, diabetes status, or underlying renal pathology." (PMID 40881125, 2025). "Elevated RBP4 levels have been associated with markers of inflammation and oxidative stress in individuals with DKD, suggesting that RBP4 may contribute to the pathogenesis of kidney damage in diabetes." (PMID 38791060, 2024). "RBP4 might be a predictor for the onset of diabetes in shift workers in the coming future." (PMID 37312059, 2023). "Last but not least, transthyretin may cause diabetes by altering retinol binding protein 4 (RBP4)-transthyretin binding." (PMID 35889910, 2022). "Nevertheless, the RBP4-diabetes association was not different by menopausal status in our study." (PMID 30651745, 2019). "In addition, it is well established that serum RBP4 is increased in patients with chronic renal failure, making renal clearance a relevant confounding factor for serum RBP4 concentrations in patients with diabetes or renal disease." (PMID 20932285, 2010). "Among the participants of the same age, gender, BMI, diabetes, PSQI, family income, smoking and drinking, the RBP4 level of shift workers increased by an average of 9.51 μg/mL compared with the non-shift workers." (PMID 37312059, 2023). "The multivariate linear mixed model showed that when age, gender, BMI, diabetes, PSQI, family income, smoking and drinking remained unchanged, the RBP4 level of the shift workers increased by an average of 9.51 μg/mL compared with the day workers." (PMID 37312059, 2023). "A similar AuNPs aggregation strategy was introduced for capturing retinol-binding protein 4 (RBP4), a potential biomarker for the early diagnosis of type 2 diabetes mellitus." (PMID 37232930, 2023). "Other molecules which were differentially released by epicardial fat from patients with diabetes and CAD were apolipoprotein A-I or retinol binding protein 4 (RBP4), indicators of cardiovascular events." (PMID 35887234, 2022).
diabetes (continued). "We identified the significant T2DM targets of Asian propolis, namely retinol-binding protein-4 (RBP4) and aldose reductase (AKR1B1) that have important roles in insulin sensitivity and diabetes complication, respectively." (PMID 35807241, 2022). "This in silico study revealed that the six known compounds have good inhibitory action to T2DM targets, namely, RBP4 and AKR1B1, which contribute in improving insulin sensitivity and prevent diabetes complication, respectively." (PMID 35807241, 2022). "Targeting RBP4, FABP4 or their signaling pathway to treat diabetes or atherosclerosis has been a profuse topic for the last few years." (PMID 34638803, 2021). "We further discovered marked changes in prediabetes/diabetes-related proteins (AACT/SERPINA3, AAT/SERPINA1, ApoA-I, HP, RBP4, TTR, and ZAG)." (PMID 31504048, 2019). "Solute carrier family 2 member 4- (SLC2A4-) retinol binding protein-4- (RBP4-) phosphoenolpyruvate carboxykinase 1 (PCK1)/phosphoinositide 3-kinase (PI3K) is an adipocyte derived “signalling pathway” that may contribute to the pathogenesis of type 2 diabetes mellitus (T2DM)." (PMID 30805369, 2019). "Based on rGFR stratum, among the three diabetic subgroups, age, diabetes duration, percentage of hypertension, WC, SBP, RBP4, UACR, and FABP4 all increased with the decrease in rGFR (all P < 0.05)." (PMID 29992142, 2018). "Regulation of TTR and RBP-4 is also interesting given previous relationships between the TTR/RBP-4 complex and diabetes." (PMID 28670222, 2017). "Retinol-binding protein 4 (RBP4), a novel adipokine secreted by adipocytes and the liver, has elevated levels in type 2 diabetes mellitus (T2DM)." (PMID 24559154, 2014). "Subsequently, correlation analysis revealed a bifurcated adipokine landscape—classical regulators EP, ITLN1, and RBP4 were observed in both datasets, plus LEP in diabetes—maintaining strong positive ties to mitochondrial hubs, signifying a conserved energy–support axis." (PMID 40869253, 2025). "Retinol binding protein 4 (RBP-4), alongside glycated albumin (GA), glycated human serum albumin (GHSA) and the GHSA to human serum albumin (HSA) ratio, belongs to a group of specific biomarkers that can predict the diabetes condition even better than glucose." (PMID 38392020, 2024). "In addition, since RBP4 levels are elevated in the serum of thin, non-diabetic but insulin-resistant individuals with a high genetic risk of developing type 2 diabetes, RBP4 may be useful as an early marker of diabetes risk." (PMID 38966226, 2024). "In a cross-sectional study of 137 patients (77 HS patients and 60 controls) without diabetes mellitus, higher RBP4 and lower ghrelin levels were found in HS." (PMID 36499573, 2022). "Our meta-analysis revealed that circulating RBP4 levels were elevated only in patients with diabetic kidney diseases, rather than in simple diabetes subjects without DN." (PMID 33082885, 2020). "Genes (Apo family, Lcn2, and Rbp4, etc.)involved in lipid transport showed opposite expression profiles between the diabetes-DFE-VS-diabetes and diabetes-VS-normal comparisons, suggesting their critical roles in decreasing lipid infiltration under DFE administration." (PMID 31790971, 2020). "In people without diabetes at the baseline, resistin and RBP4 levels were significant predictors of type 2 diabetes development at 10 years." (PMID 31690939, 2020). "In univariate regression analysis, RBP4 was strongly correlated with retinol in all subjects combined, and this relationship did not vary according to diabetes status." (PMID 31717719, 2019). "Initial studies observed elevated RBP4 levels in T2DM patients, whereas more recent reports either detected no abnormalities in RBP4 or even found a negative correlation of RBP4 with diabetes status." (PMID 31717719, 2019). "The aim of the present study was to evaluate the role of RBP4 in Chinese patients with type 2 diabetes mellitus with and without diabetic retinopathy (DR)." (PMID 30135138, 2018).
diabetes (continued). "Further subgroup analysis did not reveal any influence of gender, diabetes or statins’ usage on RBP4 levels within both CAD and non-CAD groups (p > 0.05)." (PMID 25142320, 2014). "RBP4 concentrations in patients with diabetes were not correlated with insulin sensitivity as calculated by the HOMA-IR (r = 0.473, p = 0.218)." (PMID 24099047, 2013). "In contrast, BMI, LDL, waist circumference, CRP, leptin, A-FABP and RBP-4 did not differentiate the types of diabetes." (PMID 22164267, 2011). "We show here that the circulating RBP4 level in ICU patients is not the result of preexisting diabetes or glucose intolerance (as reflected by HbA1c or plasma glucose)." (PMID 20932285, 2010). "This study aimed to investigate the levels of Retinol Binding Protein 4 (RBP4), Lipocalin-2, and high-sensitivity C-reactive protein (hsCRP) in individuals with impaired fasting glucose (IFG), impaired glucose tolerance (IGT), and type 2 diabetes mellitus (T2DM)." (PMID 40951890, 2025). "Existing research has shown that retinol binding protein(RBP4) has an impairing effect on arterial elasticity and induces insulinresistance, but the clinical value of RBP4 in patients with coronary heartdisease (CHD) combined with type 2 diabetes mellitus (T2DM) has not beeninvestigated." (PMID 39077416, 2023). "Retinol binding protein 4 (RBP4), a biomarker for insulinresistance in type 2 diabetes (DM), is increased in heart failure." (PMID 39076230, 2022). "The correlation of RBP4 with TSH (r = 0.241; P = 0.004) and T3 (r = -0.158; P = 0.018) remained significant even after adjustments for potential confounders including age, sex, smoking, hypertension, diabetes, BMI, and the levels of Cr, FBG, TC, TG, HDL-C, and LDL-C." (PMID 31278889, 2019). "With this AUC, RBP4 presented a greater discriminatory ability to diagnose VTDR compared with HbA1c (AUC 0.76; 95% CI: 0.70–0.82; P<0.001), Hs-CRP (AUC 0.71; 95% CI: 0.65–0.78; P<0.001), diabetes duration (AUC 0.77; 95% CI: 0.71–0.83; P<0.001), and HOMA-IR (AUC 0.80; 95% CI: 0.74–0.86; P<0.001)." (PMID 30135138, 2018). "With this AUC, RBP4 presented a greater discriminatory ability to diagnose DR compared with HbA1c (AUC 0.71; 95% CI: 0.63–0.78; P<0.001), Hs-CRP (AUC 0.65; 95% CI: 0.59–0.72; P<0.001), diabetes duration (AUC 0.62; 95% CI: 0.55–0.69; P<0.001), and HOMA-IR (AUC 0.73; 95% CI: 0.68–0.80; P=0.005)." (PMID 30135138, 2018). "Furthermore, the combined model II (RBP4/HOMA-IR/diabetes duration/Hs-CRP/HbA1c) did not improved the ability of model I to diagnose VTDR (AUC of the combined model 0.94; 95% CI: 0.86–0.96; P>0.05)." (PMID 30135138, 2018). "In summary, our results suggest that serum RBP4 may negatively affect β-cell function in Chinese women NAFLD patients without known diabetes mellitus." (PMID 24160775, 2013). "Circulating levels of lipocalin-2 and RBP4 are positively correlated with carotid IMT and subclinical atherosclerosis in type 2 diabetes, which suggests a potential role of these two lipid-binding chaperones in the pathogenesis of vascular complications of diabetes." (PMID 23799122, 2013). "To determine which fat compartments are associated with elevated RBP4 levels in humans, we measured serum RBP4 and hepatic fat content (HFC), visceral (VFA) and subcutaneous abdominal fat area (SFA) in 106 subjects with non-alcoholic fatty liver disease (NAFLD) without known diabetes." (PMID 25890223, 2015). "In this present study, among participants without diabetes at the baseline (NGT and prediabetes), baseline RBP4 level was significantly higher in type 2 diabetes converters than nonconverters at the 10-year follow-up." (PMID 31690939, 2020). "While no other differences were shown in serum RBP4 concentrations when stratified by TNM stage, tumor metastasis, smoking status, alcohol status, diabetes and Body Mass Index (BMI)." (PMID 29190912, 2017).
diabetes (continued). "Thus, the aim of this paper was to investigate the association between serum RBP4 levels and HFC, visceral (VFA) and subcutaneous abdominal fat area (SFA), as well as other metabolic parameters in Chinese subjects with nonalcoholic fatty liver disease without known diabetes." (PMID 25890223, 2015). "Data from 284 Saudi subjects, grouped into healthy, obese diabetes, non-obese diabetes, obese non-diabetes and patients with CVD, provide evidence supporting a biomarker role for serum RBP4 for CVD." (PMID 23119072, 2012). "Additionally, RBP4 levels are related to large VLDL and small-dense LDL subfractions in subjects with and without diabetes; mean LDL size in morbid obese patients was noticed as well." (PMID 34575030, 2021).